OR7A5 (olfactory receptor family 7 subfamily A member 5)
Description:
Odorant receptor.
Synonyms: HTPCR2
Tractability: Antibody: UniProt places it where antibodies can reach, with medium confidence; UniProt predicts a signal peptide or a membrane-spanning region; its Gene Ontology location is reachable by antibodies, with medium confidence.
Gene: Protein-coding gene on chromosome 19 (14,826,241 to 14,835,185, reverse strand). Ensembl gene ENSG00000188269.
Subcellular location: Cell membrane
Pathways (Reactome):
Sensory Perception: Expression and translocation of olfactory receptors
Gene Ontology:
Molecular function: olfactory receptor activity; G protein-coupled receptor activity; signaling receptor activity
Biological process: sensory perception of smell; signal transduction; detection of chemical stimulus involved in sensory perception of smell; G protein-coupled receptor signaling pathway; sensory perception of chemical stimulus
Cellular component: membrane; plasma membrane
Genetic constraint (gnomAD): Loss-of-function variants: 1 observed, 0.29 expected, observed/expected ratio (o/e) 3.48. That is too few expected variants to judge how well the gene tolerates losing a copy. Missense variants: 319 observed, 391.67 expected, observed/expected ratio (o/e) 0.81, 90% interval 0.74 to 0.89. Synonymous variants: 140 observed, 151.18 expected, observed/expected ratio (o/e) 0.93, 90% interval 0.81 to 1.07.
Homologues: Orthologues: chimpanzee OR7A5 (99% identical), macaque OR7A17 (78% identical), dog OR7A52 (77% identical), dog OR7A26 (76% identical), dog OR7A54 (76% identical), dog OR7A23 (75% identical), dog OR7A74 (74% identical), dog OR7A58 (74% identical), dog OR7A53 (73% identical), dog OR7A69 (73% identical), mouse Or7a40 (72% identical), dog OR7A60 (70% identical), and 6 more. Paralogues in human: OR7A10 (77% identical), OR7A17 (77% identical), OR7D4 (67% identical), OR7C1 (66% identical), OR7C2 (64% identical), OR7G2 (62% identical), OR7D2 (62% identical), OR7E24 (61% identical), OR7G3 (61% identical), OR7G1 (58% identical), OR1G1 (57% identical), OR1J4 (52% identical), and 116 more.
Diseases named in the same sentence as OR7A5 in open-access papers:
OR7A5 is named in the same sentence as 1 disease in open-access papers, as found by Europe PMC text mining. Sharing a sentence is not in itself a finding about the gene and the disease. The quoted sentences say what the papers report.
leukaemia (1 paper, 2020). "Currently, data of OR7A5 and OR7C1 in leukaemia are not reported." (PMID 32817744, 2020).